GAPDH (glyceraldehyde-3-phosphate dehydrogenase)
Diseases named in the same sentence as GAPDH in open-access papers (continued):
Sharing a sentence is not in itself a finding about the gene and the disease.
lymphoma (12 papers, 2009 to 2025). A malignant (clonal) proliferation of B- lymphocytes or T- lymphocytes which involves the lymph nodes, bone marrow and/or extranodal sites. "Since resemblance with AITL was striking, these authors analyzed the Tfh plck-GAPDH lymphoma cells for mutations in RhoA, Tet2, Idh2, and Dmt3a, frequently mutated in these patients." (PMID 32796826, 2020). "The link between KMT2D and glycolysis may be relevant and worth to explore in detail in lymphoma, as glycolysis measured by expression of aldolase A and GAPDH was associated with significantly shorter transformation-free survival in FL patients." (PMID 35071240, 2021). "High expression of aldolase A and GAPDH may indicate increased metabolic turnover, and these enzymes may be useful biomarkers in primary FL for predicting the risk of subsequent lymphoma transformation." (PMID 35071240, 2021). "In GC B cells, the non-canonical NFκB pathway is activated through PD1–PDL1 ligation, which likely contributes to AITL-like lymphoma development in GAPDH-overexpressing mice." (PMID 32704161, 2020). "The remaining question was though how did GAPDH overexpression in T cells lead to this AITL lymphoma?" (PMID 32796826, 2020). "Analysis of expression profile of newly diagnosed DLBCL has showed that glyceraldehyde-3-phosphate dehydrogenase (GAPDH) is related to metabolic profile of lymphoma cells." (PMID 33409153, 2020). "It was recently reported that mice with GAPDH overexpression in T cells develop Tfh lymphoma with AITL-like features by the age of 18 months or older." (PMID 32704161, 2020). "Our data indicated that proliferating lymphoma cells down-expressed GAPDH and B2M, but after GM treatment, useful for inducing cell death, the gene expression increased." (PMID 25622250, 2015). "Expression was variable in both normal and lymphoma samples, ranging from 0 to 3.03 relative to the GAPDH expression within the matching sample." (PMID 19912643, 2009). "Moreover, the GAPDH-dependent metabolic reprogramming strongly limited the capacity of either phenformin or L-asparaginase to induce apoptosis of Eμ-Myc murine lymphoma cells." (PMID 39941763, 2025). "GAPDH is reported to maintain intact mitochondria and facilitate tumor survival and chemotherapeutic resistance, and its deregulated expression assists in the vascularization and aggressiveness of lymphoma." (PMID 35804814, 2022). "Using a protease digestion assay, we observed the presence of GAPDH on the outer surface of EVs isolated from HEK293T, HeLa, MSCs, SKOV-3 and B16 lymphoma cells." (PMID 34795295, 2021). "Consistent with our previous findings, we see that silvestrol blocks the translation of the MYC and BCL2 mRNAs, without affecting the GAPDH housekeeping gene, across several lymphoma lines (SuDHL-4, SuDHL-6, SuDHL-10, Ly8)." (PMID 33562682, 2021). "Additionally, MRP4 expression level was the highest in the lymphoma cell line U937 (23 copies/103 GAPDH) and the blood cell line derived from a healthy subject RPMI 1788 (12 copies/103 GAPDH)." (PMID 23181130, 2012). "However, in the plck-GAPDH lymphoma a dominant upregulation of the noncanonical NF-κB pathway was detected." (PMID 32796826, 2020).
malaria (12 papers, 2013 to 2024). Malaria is a serious and sometimes fatal disease caused by a parasite that commonly infects a certain type of mosquito which feeds on humans. "It has been reported that plasmodium GAPDH showed interesting potential as a malaria diagnostic biomarker." (PMID 31355216, 2019). "Interestingly, a recent study explored the role of GAPDH as a new malaria diagnostic biomarker for P. falciparum." (PMID 32122317, 2020). "GAPDH is involved in glucose metabolism and host cell entry, and was recently proposed as a biomarker for malaria." (PMID 38297098, 2024). "Glyceraldehyde 3-phosphate dehydrogenase (GAPDH) of the malaria parasite Plasmodium falciparum is inhibited by heme with a Ki of 0.2 μM." (PMID 38183476, 2024). "We find that FSM dramatically alters metabolic balance in malaria parasites, such that metabolites upstream of GAPDH are elevated relative to metabolites downstream." (PMID 36103572, 2022). "We have thus identified an unusual metabolic regulation scheme in the malaria parasite through the essential glycolytic enzyme, glyceraldehyde 3-phosphate dehydrogenase (GAPDH)." (PMID 36103572, 2022). "Glycolytic proteins such as PGK (phosphoglycerate kinase), Protein disulfide isomerase and GAPDH (Glyceraldehyde 3-phosphate dehydrogenase), previously reported in the context of malaria were detected in plasma with high confidence." (PMID 32122317, 2020). "Anti-peptide antibodies against unique peptides in the amino acid sequence of malaria LDH or GAPDH were shown to differentiate between the proteins." (PMID 29505599, 2018). "It is likely that the reversible H2O2-induced decrease in [ATP]i observed in the malaria parasites occurs through a similar inhibition of glyceraldehyde-3-phosphate dehydrogenase, though this is yet to be demonstrated directly." (PMID 23536836, 2013). "GAPDH of the malaria parasite is reportedly inhibited by low concentrations of heme." (PMID 38183476, 2024). "S-glutathionylation patterns in P. falciparum have already been thoroughly studied and indicate redox regulation in the malaria parasite: GAPDH and pyruvate kinase were shown to be inhibited by S-glutathionylation, which is comparable to the present data on PfHK." (PMID 37628920, 2023). "The phage display approach led to the identification of a peptide that structurally mimics glyceraldehyde-3-phosphate dehydrogenase (GAPDH) on the surface of Plasmodium sporozoites; this peptide became a new vaccine candidate for targeting malaria liver invasion." (PMID 35359712, 2022). "During malaria, GAPDH is expressed during asexual blood stage at the apical end of merozoites where it may be involved in membrane trafficking and vesicular transport." (PMID 28935714, 2017). "A human anti-malaria antibody pool was passed consecutively over four affinity resins with recombinant P. falciparum LDH, GAPDH, Cox17 and PMT coupled to the resins." (PMID 29505599, 2018). "A recently identified new P. falciparum biomarker, glyceraldehyde-3-phosphate dehydrogenase (GAPDH) has two unique P. falciparum GAPDH epitopes and an epitope common to GAPDH from all malaria species." (PMID 29505599, 2018).
myeloma (11 papers, 2015 to 2025). "However, dysregulation of GAPDH expression in MRONJ in patients with multiple myeloma should be approached with caution, as GAPDH is implicated in multiple cancer-related biological processes, having recently emerged as a primary focus in cancer research." (PMID 41465220, 2025). "Scientists analyzed gene expression data from individuals with multiple myeloma derived from microarray experiments and identified seven hub genes (ACTB, FN1, GAPDH, JUN, PTPRC, STAT3, and TNF) linked to bisphosphonate-induced osteonecrosis of the jaw." (PMID 41465220, 2025). "The authors examined gene expression data of individuals with multiple myeloma obtained from microarray experiments and discovered seven hub genes (ACTB, FN1, GAPDH, JUN, PTPRC, STAT3, and TNF) associated with bisphosphonate-induced osteonecrosis of the jaw." (PMID 39596473, 2024). "Consequently, the alteration of GAPDH expression in MRONJ in patients with multiple myeloma should be approached with caution." (PMID 39596473, 2024). "In patients, various amounts of RELN was found in CD138+ myeloma cells and a hierarchical cluster analysis with Ward's method was used to analyze the relative expression fold of RELN (compared with the GAPDH control)." (PMID 26848618, 2016). "cDNA was prepared from the KMS-11 and OCI-My5 cell lines and from primary CD138+ myeloma cells from four subjects, and a specific 144 bp fragment of the human MPL gene and a 797 bp fragment of the GAPDH gene were amplified by PCR." (PMID 25886818, 2015). "To find a suitable human myeloma cell line for in vitro assays and an in vivo study, we quantified the gene expression of HGF in 5 human myeloma cell lines and healthy plasma cells by real-time PCR, relative to the housekeeping gene GAPDH." (PMID 29924867, 2018). "Interestingly, we originally compared MYC mRNA levels in cell lines and primary cells applying GAPDH mRNA as the only reference, getting higher MYC levels in primary cells than in myeloma cell lines." (PMID 26087190, 2015). "DTT treatment induced degradation of WT BLOC1S1 but not G444C BLOC1S1 in myeloma cells, as observed by a decrease in total BLOC1S1 and qTag expression in WT-transduced cells and an increase in BLOC1S1 and qTag expression relative to GAPDH in G444C-transduced cells." (PMID 25870107, 2015).
Insulin resistance (9 papers, 2006 to 2022). Increased resistance towards insulin, that is, diminished effectiveness of insulin in reducing blood glucose levels. "It is likely that the insulin resistance-associated downregulation of glycolytic enzymes, including GAPDH, and the associated worsening of the Aβ and Tau pathology play a major role in GAPDH dysfunction, subsequent glyceraldehyde-derived AGE formation, oxidative stress and inflammation." (PMID 36117625, 2022). "The interaction between the glycolytic protein GAPDH and the inflammatory protein small ubiquitin-like modifier 4 has been shown to induce insulin resistance in diabetic and obese individuals." (PMID 36187097, 2022). "In our study, the correlation analysis revealed notable relevance of both elevated AHR (r = 0.6188, ***P < 0.0001, Pearson analysis) and RORC (r = 0.2541, *P = 0.0289, Pearson analysis) (relative to GAPDH) mRNA expression to increased insulin resistance." (PMID 32849564, 2020). "GAPDH monomer combined with body mass index (BMI) and PRDX2 S-S dimer combined with homeostatic model assessment for insulin resistance (HOMA-IR) showed to be very promising biomarkers to predict OSA and OSA severity, respectively." (PMID 33256145, 2020). "The mRNA expression levels of RAGE, NF-kB, NRF2, and GAPDH were determined in PBMC by qPCR in 20 obese (OB), 17 obese with insulin resistance (OB-IR), and 20 healthy subjects (HS), matched by age and sex." (PMID 31231489, 2019). "The interaction between the glycolytic protein GAPDH and inflammatory SUMO4 suggests a potential role in the development of insulin resistance." (PMID 19997558, 2009).
multiple sclerosis (8 papers, 2016 to 2024). A progressive autoimmune disorder affecting the central nervous system resulting in demyelination. "For fumarate, its succination of GAPDH in immune cells was suggested to underlie the immunomodulatory activity of dimethylfumarate, an FDA-approved drug to treat multiple sclerosis, an auto-immune inflammatory disease." (PMID 39592957, 2024). "Indeed, dimethyl fumarate, an immunomodulatory drug used to treat psoriasis and multiple sclerosis, was recently shown to mediate anti-inflammatory effects through inactivating the glycolytic enzyme glyceraldehyde 3-phosphate dehydrogenase (GAPDH) in activated myeloid and lymphoid cells." (PMID 38834617, 2024).
asthma (7 papers, 2010 to 2024). "In contrast, CDp40-treated mice displayed aggravated airway inflammation in experimental asthma, revealing the different immunomodulatory abilities between probiotic and pathogenic GAPDH proteins." (PMID 36175886, 2022). "In contrast, CDp40, the GAPDH from pathogenic C. difficile, promoted asthma exacerbation." (PMID 36175886, 2022). "Quantitative PCR was used to monitor the impact of storage conditions on the expression of housekeeping genes: GAPDH and β-actin, and the asthma related genes: POSTN and FBN2." (PMID 38948078, 2024). "According to the median mRNA expression of TFR1 relative to that of GAPDH, we divided the asthma patients into a TFR1 low expression group and a TFR1 high expression group." (PMID 35602900, 2022). "However, CDp40, GAPDH isolated from Clostridium difficile did not possess this anti-asthma effect." (PMID 36175886, 2022). "It has been reported that GAPDH and ACTB were not suitable as RGs for quantitative analysis of gene expression in asthma, which has similar pathophysiology to CRS26." (PMID 29371606, 2018).
autoimmune disease (7 papers, 2017 to 2025). A disorder resulting from loss of function or tissue destruction of an organ or multiple organs, arising from humoral or cellular immune responses of the individual to their own tissue constituents. "GAPDH is already reported as a protein implicated in numerous autoimmune disorders." (PMID 30224677, 2018). "In conclusion, the multiplicity of functions of GAPDH in pathologies, from cancer to neurodegenerative and autoimmune diseases, demands appropriate therapeutic methods of the modulation of the enzyme function." (PMID 32370188, 2020). "According to the previous reports, GAPDH was identified as a target antigen reacting with the serum from patients with autoimmune diseases, such as SLE, Behçet's disease (BD), dermatomyositis (DM), rheumatoid arthritis (RA), and Takayasu's arteritis (TA)." (PMID 31049359, 2019). "Dimethyl fumarate (DMF), a glyceraldehyde-3-phosphate dehydrogenase (GAPDH) inhibitor, which has been shown to treat autoimmune diseases, was found to promote oxPPP by increasing G6PD expression in tumor cells." (PMID 39859324, 2025). "Anti-GAPDH autoantibodies are not specific for m-ASD, and have been described in autoimmune diseases such as systemic lupus erythematosus (SLE), and have been related to cognitive dysfunction in these patients." (PMID 36816132, 2023).
depression (7 papers, 2020 to 2024). "Taking into account both the function and localization of GAPDH in the cell and the obtained results, it can be concluded that GAPDH expression is altered in the states of chronic stress, and it can also be assumed that these mechanisms play a role in depression." (PMID 35448030, 2022).
HIV-1 infection (7 papers, 2010 to 2024). The type species of lentivirus and the etiologic agent of acquired immunodeficiency syndrome (AIDS). "Furthermore, herein we show that HIV-1 infection caused changes in microRNA that disrupt homeobox HOXB3 versus control GAPDH messenger RNA, with the consequences of inhibiting hematopoiesis due to the loss of HOXB3 messenger RNA expression." (PMID 38721526, 2024). "We conclude that GAPDH is incorporated into virions and that this negatively regulates HIV-1 infection by reducing LysRS and tRNALys3 packaging efficiency." (PMID 23237566, 2012). "For example, a higher expression of genes encoding the chemokine CCL5, heme oxygenase-1 (HMOX-1), thioredoxin reductase, peroxiredoxins, glyceraldehyde-3-phosphate dehydrogenase (GAPDH), etc. are host defense mechanisms well known to negatively regulate HIV-1 infection and replication (77, –, 81)." (PMID 25406321, 2015). "Taken together, these results indicate that GAPDH negatively regulates HIV-1 infection, and small molecules that reconstitute the binding mode of GAPDH to Pr55gag and p160gag-pol may interrupt Pr55gag-LysRS or p160gag-pol-LysRS interactions." (PMID 23237566, 2012). "However, human homologues of these proteins, such as chaperone protein DnaK (Hsp70), enolase (ENO), elongation factor TU (EFTU), and glyceraldehyde-3-phosphate dehydrogenase (GAPDH), are involved during HIV-1 infection." (PMID 35145925, 2021). "Surprisingly, regardless of HIV-1 infection, in the cellular pool, GAPDH was identified as six isozymes that contain an additional isozyme (spot vi (pI 8.68)) with five isozymes packaged inside the virions." (PMID 23237566, 2012). "In order to display HIV-1 infection kinetics, real-time quantitative PCR was also utilized to determine levels of intracellular HIV-1 viral mRNA normalized by cell number (house keeping gene GAPDH) at different time points following infection." (PMID 20356381, 2010). "Therefore, in this study, we examined whether GAPDH and ENO1 expression levels were changed by HIV-1 infection." (PMID 32917235, 2020).
ischemia (7 papers, 2012 to 2018). A hypoperfusion of the BLOOD through an organ or tissue caused by a PATHOLOGIC CONSTRICTION or obstruction of its BLOOD VESSELS, or an absence of BLOOD CIRCULATION. "In the present study, we evaluated the stability of six candidate reference genes (HPRT, β-actin, Sdha, GAPDH, 18S and cyclophilin) in two ischemia models: N2a cells at several time points after OGD/R injury and the intraluminal filament model of MCAO in C57 mice." (PMID 29390963, 2018). "Similarly, the nuclear translocation of GAPDH was also enhanced in the ischemia group and the ischemia-induced enhancement was inhibited by the application of the TAT-GAPDH2–2–1–1 peptide." (PMID 24670206, 2014). "Therefore, we assessed the effectiveness of the GluR2NT1-3–2 peptide to rescue cells from neurotoxic stress in the OGD model to verify the implication of the GluR2/GAPDH interaction in ischemia." (PMID 22537872, 2012). "Protein to protein interaction network analysis showed glycolytic enzymes, such as isoform alpha-enolase of alpha-enolase, isoform 1 of triosephosphate isomerase and glyceraldehyde-3-phosphate dehydrogenase, had more connections than other proteins in myocardial metabolism during ischemia." (PMID 22443514, 2012). "Therefore, to test our hypothesis that GAPDH acts as a mitochondrial trans-S-nitrosylase, we examined mitochondrial fractions from control hearts and IPC hearts subjected to ischemia/reperfusion injury (IPC-IR), for evidence of mitochondrial GAPDH using mass spectrometry." (PMID 25347796, 2014). "The target/reference (BCL-2/GAPDH) mean ratio was 0.58 ± 0.16 for control group and 1.14 ± 0.13 for treatment group.Therefore, this study was undertaken to reveal the effect of the pentoxifylline on BCL-2 gene expression changes in kidney after a period of ischemia or lack of oxygen in rats." (PMID 24734070, 2014).
leukemia (7 papers, 2010 to 2021). A malignant (clonal) hematologic disorder, involving hematopoietic stem cells and characterized by the presence of primitive or atypical myeloid or lymphoid cells in the bone marrow and the blood. "The lower expression of GAPDH in lanes 1 and 2 is consistent with much higher total protein expression by 293 cells compared to primary leukemia cells, and thus a lower percentage of GAPDH in a 30 ug gel sample." (PMID 32040482, 2020). "Imatinib treatment decreased the activity of both HK and GAPDH in leukemia and myeloid tumors." (PMID 27582538, 2016). "These dendrimers silenced glyceraldehyde 3-phosphate dehydrogenase (GAPDH) expression and reduced HIV replication in PBMC and human leukemia T lymphocytes, remaining at a low cytotoxicity level." (PMID 34281151, 2021). "qRT-PCR was performed for each of the 14 new genes, as well as for 5 standard control genes (GAPDH, ACTB, TBP, HPRT1, ABL1), on cDNA from a panel of 14 leukemia samples (10 AML, 4 ALL) plus one CD34+ cord blood sample (using equal amounts of RNA)." (PMID 24069164, 2013). "CBD/siRNA complexes transfected lymphocytes and silenced the expression of glyceraldehyde 3-phosphate dehydrogenase (GAPDH), and reduced HIV replication in human leukemia T lymphocytes and primary peripheral blood mononuclear cells (PBMC), with low cytotoxicity." (PMID 34281151, 2021). "We performed STAMP analysis of a human leukemia-derived cell line, M091 and evaluated STAMP results at loci that we knew to be transcriptionally silenced, (CDKN2B, p15INK4b), or robustly expressed (GAPDH)." (PMID 21267076, 2011).